IRF1 (interferon regulatory factor 1)
Diseases named in the same sentence as IRF1 in open-access papers (continued):
Sharing a sentence is not in itself a finding about the gene and the disease.
myasthenia gravis (2 papers, 2020 to 2025). Myasthenia gravis (MG) is a rare, clinically heterogeneous, autoimmune disorder of the neuromuscular junction characterized by fatigable weakness of voluntary muscles. "Herein, we explored the function of interferon regulatory factor 1 in myasthenia gravis, with an aim to understand the underlying mechanisms." (PMID 41169211, 2025). "Eight associations (five variants) were not previously reported to our knowledge, including associations near IRF1/IL5 for myasthenia gravis, near TNFSF11 for RF− JIA, and near CD2/CD28 for EGPA." (PMID 33239102, 2020). "Next, T and B cells from peripheral blood were co-cultured to explore the interferon regulatory factor 1-related mechanisms in myasthenia gravis." (PMID 41169211, 2025). "Together, these findings indicate the important role of interferon regulatory factor 1 in myasthenia gravis and suggest its molecular mechanisms." (PMID 41169211, 2025). "Collectively, our results suggest that interferon regulatory factor 1 enhances T cell differentiation by recruiting histone deacetylase 1 to block B cell CD180 transcription in myasthenia gravis via the Toll-like receptor 4/mitogenactivated protein kinases/nuclear factor-kappa B pathway." (PMID 41169211, 2025).
myelogenous leukemia (2 papers, 2021 to 2023). "ENCFF020ODE is the interferon regulatory factor 1 (IRF1) ChIP-seq data from human K562 cells, a human immortalized myelogenous leukemia cell line, treated with Interferon gamma (IFN-γ)." (PMID 38032891, 2023).
myocardial infarction (2 papers, 2015 to 2023). Gross necrosis of the myocardium, as a result of interruption of the blood supply to the area, as in coronary thrombosis. "In the present study, we show that the pro-inflammatory polarization of macrophages in myocardial infarction is associated with IRF1 modulation and identify 5AZ as a potential pharmacological therapy to protect cardiac function." (PMID 26510961, 2015).
myositis (2 papers, 2014 to 2020). "In this study, we could identify in the myositis transcriptomes only IFNγ but not IFNα as a predominant trigger for PSMB8/-9, which also correlated with the expression of STAT1 and IRF-1." (PMID 25098831, 2014).
nephrocalcinosis (2 papers, 2020). Nephrocalcinosis is a disorder that occurs when too much calcium is deposited in the kidneys. "IRF1 might potentially serve as a therapeutic target for the regulation of macrophage polarization and CaOx-induced nephrocalcinosis." (PMID 33204326, 2020).
Osteochondroma (2 papers, 2020 to 2024). A common, benign cartiliginous neoplasm arising from the metaphysis of bone. "In this pathway, IRF-1 was up-regulated by RARγ agonist treatment in both osteochondroma explant cultures and polydactyly chondrocytes." (PMID 32294904, 2020).
rectal cancer (2 papers, 2014 to 2022). A primary or metastatic malignant neoplasm that affects the rectum. "A previous study examined genetic variation in IFNG, IFNGR1, IFNGR2 and IRF1-9 with the risk and survival of colon and rectal cancer." (PMID 25350395, 2014).
Rotavirus infection (2 papers, 2019 to 2020). Infection with any of the rotaviruses. "Thus, in this study, we have dissected the effects of the cellular translation machinery, the eIF4F complex, on rotavirus infection, and we found that the eIF4F complex is an essential host factor in counteracting rotavirus infection through regulating the antiviral protein IRF1 and IRF7." (PMID 30934842, 2019). "It is also important to note that TNF, a multi-functional proinflammatory cytokine, was repressed by both rotavirus and coronavirus, but IRF1, which is required to activate type I IFN responses, was activated following rotavirus infection." (PMID 31838832, 2020). "Mechanically, we confirmed that the silence of the eIF4F complex suppressed the protein level of IRF1 and IRF7 that exert potent antiviral effects against rotavirus infection." (PMID 30934842, 2019).
Salmonella Infections (2 papers, 2019 to 2025). Infections with bacteria of the genus SALMONELLA. "A network analysis identified an interaction between the Toll-like receptor pathway and Salmonella infection via TLR4 and TLR2, the NOD-like receptor pathway and Salmonella infection via GBP1, and the TNF signaling pathway and Salmonella infection via IRF1." (PMID 40005871, 2025).
tendinopathy (2 papers, 2022 to 2023). "NF-κB expression is also dependent on IRF1 activation, and increased NF-κB levels are detected in early RC tendinopathy." (PMID 36499497, 2022). "Additionally, increased IRF1 expression is also found in tendinopathy." (PMID 36499497, 2022). "Tenocytes can be transformed from a quiescent state to an activated state by the inflammatory reaction of tendinopathy, being hypertrophic ones and highly expressing molecular markers such as toll-like receptor 4 (TLR4), interferon regulatory factor 1 (IRF1), IRF5, PDPN, CD106, and CD248." (PMID 37545895, 2023).
testicular germ cell tumor (2 papers, 2011 to 2025). A germ cell tumor arising from the testis. "In testicular germ cell tumors (TGCT), UBD expression was significantly positively correlated with SYK, PI3K p85, IRF1, PKC-panbeta II (phosphorylated at S660), and STAT5α." (PMID 41347086, 2025).
uveitis (2 papers, 2023 to 2025). An inflammatory process affecting a part of or the entire uvea. "This study identified six significantly upregulated genes (CDKN1A, VCAM1, NFKBIA, ICAM1, IRF1, and CXCL10) and demonstrated that QHRGF exerts therapeutic effects on uveitis using in vivo experiments." (PMID 40718791, 2025). "Our observations suggest the possibility of developing therapeutics directed against C2CD4B or IRF1 for non-infectious uveitis involving the posterior eye." (PMID 36834715, 2023).
abscess (1 paper, 2013). An inflammatory process characterized by the accumulation of pus within a newly formed tissue cavity which is the result of a bacterial, fungal, or parasitic infection or the presence of a foreign body. "The IFN-γ responsive gene IRF-1 was responsible for subsequent activation of chemokines and adhesion molecules that recruited neutrophils to the site of infection and consequently aroused inflammatory tissue injury and abscess formation." (PMID 24223208, 2013).
adenovirus infection (1 paper, 2020). "However, a separate study has reported that Dkk3-carrying adenovirus infection of normal human fibroblasts induced interleukin-7 production, triggered by ER stress proteins (ASK1, p38, IRE1α and IRF-1)." (PMID 33425757, 2020).
adrenocortical carcinoma (1 paper, 2022). "IRF-1 expression was downregulated in adrenocortical carcinoma (ACC), kidney chromophobe (KICH), LUAD, and LUSC." (PMID 35092496, 2022).
airway allergy (1 paper, 2017). "Thus IFN-γ/IRF1 signalling restricts Th9-mediated airway allergy in an IL-9-dependent manner while enhancing IFN-γ production in Th9 cells, indicating that IRF1 constrains allergic airway disease by skewing Th9 cells towards a ‘low-allergic' IFN/Th9 phenotype." (PMID 28497800, 2017).
alcoholic liver cirrhosis (1 paper, 2023). A disorder of the liver characterized by the presence of fibrotic scar tissue instead of healthy liver tissue. "IRF1 mono was more enriched in PBMCs than in the liver tissues of patients with alcoholic liver cirrhosis; however, it was generally more enriched in healthy individuals." (PMID 36845083, 2023). "Therefore, our findings suggest that RNASE2 mono, IRF1 mono, IL1R2 mono, and H1-4 mono could be the origin of macrophages and may transform into two distinct types of monocytes and macrophages during the progression of alcoholic cirrhosis." (PMID 36845083, 2023).
allergic asthma (1 paper, 2017). A asthma with a basis in a pathological type I hypersensitivity reaction. "Consistently, IRF1 restricts the IL-9-dependent pathogenicity of Th9 cells in a mouse model of allergic asthma." (PMID 28497800, 2017). "Accordingly, the absence of IRF1 in IFN-γ-treated Th9 cells led to increased IL-9-dependent pathogenicity in AAD, a mouse model for allergic asthma." (PMID 28497800, 2017).
atypical ductal hyperplasia (1 paper, 2011). Atypical ductal hyperplasia is an atypical proliferative lesion that falls in between the continuum from normal hyperplasia to low grade ductal carcinoma in situ. "Formalin-fixed paraffin-embedded archival breast tissue specimens from patients with atypical ductal hyperplasia (ADH), ductal carcinoma in situ (DCIS) and invasive ductal carcinoma (IDC) were examined for their expression of IRF1 and IRF5." (PMID 22053985, 2011).
brain inflammation (1 paper, 2014). "By this IRF-1 prevents induction of inflammatory response and protects mice from fatal brain inflammation." (PMID 24675692, 2014).
brain injury (1 paper, 2017). Acute and chronic (see also brain INJURIES, CHRONIC) injuries to the brain, including the cerebral hemispheres, CEREBELLUM, and brain STEM. "Ischemic brain injury activates the pro-inflammatory transcription factor IRF1 (interferon regulatory factor 1)." (PMID 28769762, 2017).
breast adenocarcinoma (1 paper, 2014). "We next tested MCF7 cells, derived from breast adenocarcinoma, with Ad-IRF-1 treatment to see if we could detect a similar AS phenotype." (PMID 24650050, 2014).
Burkitt lymphoma (1 paper, 2025). A rare form of malignant mature B-cell non-Hodgkin lymphoma. "Our findings highlight that treatment with dEZH2 induces PD-L1 expression in PD-L1-negative Burkitt’s lymphoma, mediated by increased levels of NF-κB and IRF-1." (PMID 40308579, 2025).
Cerebral ischemia (1 paper, 2023). Restriction of arterial blood supply to the brain associated with insufficient oxygenation to support the metabolic requirements of the tissue. "Interferon regulatory factor-1 (IRF-1) has been investigated in relation to cell death and results showed a correlation between increased IRF-1 and cell death in undifferentiated SH-SY5Y cell model of cerebral ischemia (n = 1)." (PMID 37380886, 2023).
cervical tumour (1 paper, 2020). "All these results strongly suggest that HPV16 E6 rescues IRF-1-triggered apoptosis by interfering with the PI3K/PDK1/mTOR signalling pathway in cervical tumour cells." (PMID 33076322, 2020).
chronic myelocytic leukemia (1 paper, 2024). "IRF1 variants with K75E and E222K substitutions found in chronic myeloid leukemia also had reduced transcriptional activity and DNA-binding ability." (PMID 38396830, 2024).
chronic viral hepatitis (1 paper, 2025). "In line with a constitutive ISG expression in NK cells, we also showed that the expression of IFITM3, IRF1, IFIT2 and ISG20 are refractory to IFN stimulation in vitro in NK cells that were obtained from patients with HD and chronic viral hepatitis." (PMID 40837234, 2025).
clear-cell renal cell carcinomas (1 paper, 2023). "In line with our finding that SPOP could be critical for lowering the tumor-suppressive levels of IRF1, SPOP is overexpressed in most clear-cell renal cell carcinomas (ccRCC)." (PMID 37622993, 2023).
co-infection (1 paper, 2020). "There is evidence indicating that the antiviral response to PRRSV and the IBV/PRRSV co-infection uses a combination of ISGs and IRFs such as IRF1, IRF4, and IRF7 to drive the host response." (PMID 33187194, 2020). "In the case of the co-infection group, expression of both IRF1 and IRF7 may be the result of the viral sequence and etiology." (PMID 33187194, 2020).
corneal ulcer (1 paper, 2021). Area of epithelial tissue loss from corneal surface; associated with inflammatory cells in the cornea and anterior chamber. "Likewise, loss of IRF1 occurred in the lesion regions of the corneal ulcer tissues." (PMID 33414365, 2021). "Loss of interferon regulatory factor 1 and PAX6 induced by FOXC1 dysfunction is linked to the corneal ulcer." (PMID 33414365, 2021). "Loss of FOXC1, IRF1, and PAX6 was observed in some regions of the corneal ulcer tissues." (PMID 33414365, 2021). "FOXC1-depleted LSCs show the activation of an epidermis-specific gene program and the repression of IRF1 and PAX6, which are pathological characteristics of the human corneal ulcer." (PMID 33414365, 2021).
dengue (1 paper, 2022). "A non-canonical IRF-3-, IRF-5-, and IRF-7-independent antiviral defense mechanism against severe dengue, mediated by IRF-1, has been demonstrated in AG129 mice, suggesting that IRF-1 plays a role in DENV infection." (PMID 34761286, 2022).
diabetic foot ulcers (1 paper, 2023). "IRF1 can promote the proliferative, migratory, and angiogenic capacity of the HUVECs, resulting in augmented wound healing in diabetic foot ulcers." (PMID 37098476, 2023). "Intriguingly, IRF1 drives the proliferative, migratory, and angiogenic potential of the human umbilical vein endothelial cells (HUVECs), contributing to wound healing of diabetic foot ulcers." (PMID 37098476, 2023).
ductal carcinoma in situ (1 paper, 2011). "Furthermore, high-grade ductal carcinoma in situ (DCIS) or node-positive invasive ductal cancers were less likely to express IRF1 and were much more likely to have higher oncogenic IRF2 protein than normal." (PMID 22295238, 2011).
dyslipidemia (1 paper, 2017). "In the same way of IFNG, IRF1 was higher in patients without dyslipidemia." (PMID 28316372, 2017). "Patients with dyslipidemia demonstrated statistically higher expression of the IL10 and IFNA genes, while IFNG, IP10, IRF1, JAK1, and STAT3 were lower in comparison with nondyslipidemic patients." (PMID 28316372, 2017).
encephalitis (1 paper, 2014). An acute inflammatory process affecting the brain parenchyma. "IRF-1 expression in neurons prevents reoccurrence of viral replication in the brain which cause fatal encephalitis and death of the mice." (PMID 24675692, 2014). "Mice, deficient in IRF-1, are highly vulnerable to VSV infection and succumb with signs of encephalitis." (PMID 24675692, 2014). "Infected IRF-1−/− mice succumb with symptoms of fatal encephalitis." (PMID 24675692, 2014).
encephalomyelitis (1 paper, 2025). Inflammation of the brain and the spinal cord. "Research on IRF-1 in the brain has mainly focused on neuroinflammation, such as encephalomyelitis." (PMID 41029886, 2025).
endometrioid adenocarcinoma (1 paper, 2022). An adenocarcinoma characterized by the presence of malignant glandular epithelial cells resembling endometrial cells. "In a previous study on IRFs and EC, only IRF1 and EC were studied, elucidating that the expression of IRF1 is downregulated in human endometrioid adenocarcinoma compared with a normal endometrium and a postmenopausal endometrium." (PMID 35993041, 2022).
essential hypertension (1 paper, 2017). Hypertension that presents without an identifiable cause. "Hcmv-miR-UL112-3p targets MICB and IRF-1, which play critical roles in immunological, inflammatory, and anti-infection responses, and these proteins have a close relationship with essential hypertension." (PMID 28592251, 2017).
gastric tumors (1 paper, 2018). "In addition, a missense mutation in exon 2 of IRF-1 has been identified in stomach cancer." (PMID 29599126, 2018). "One such study revealed that 50% of gastric tumors exhibit LOH at the 5q region implying a critical contribution of IRF-1 to the development of stomach carcinoma." (PMID 29599126, 2018).
glaucoma (1 paper, 2025). Increased pressure in the eyeball due to obstruction of the outflow of aqueous humor. "Additionally, PPI network analysis showed that IRF1, IFI30, NR3C1 and LRRC14 have relatively abundant interacting proteins, suggesting that these genes might act as key regulatory nodes in the molecular pathways underlying HBP and glaucoma." (PMID 41170525, 2025). "The number of interacting proteins for IRF1, IFI30, NR3C1 and LRRC14 was relatively abundant, suggesting that they may play a key role in the regulatory pathways of HBP and glaucoma." (PMID 41170525, 2025).
Granuloma (1 paper, 2025). A compact, organized collection of mature mononuclear phagocytes, which may be but is not necessarily accompanied by accessory features such as necrosis. "For instance, whole transcriptome co-mapping at cellular resolution with spatial CITE-seq could validate the spatial expression patterns of CD274, IRF1, and HPSE within granulomas or inflammatory niches, clarifying their roles in local immune modulation." (PMID 40607433, 2025).
hepatoblastoma (1 paper, 2007). Hepatoblastoma (HB) is a malignant hepatic tumor and is the most common pediatric liver cancer. "Consistent with the data from Miller and co-workers we found that HCV core protein induces expression of IRF-1 in human hepatoblastoma cell lines (HepG2), but not in human fibroblast of liver origin (CHL, where IRF-1 is slightly expressed in parental cells)." (PMID 17565659, 2007).
hyperandrogenism (1 paper, 2024). Excessive secretion of androgens from the adrenal glands or gonads. "Similarly, SNPs within YAP1, TOX3 and IRF1/RAD50 were only significant in the lean group, and have previous association with ovulatory dysfunction, hyperandrogenism and increased testosterone levels respectively." (PMID 38408933, 2024).
Hyperglycemia (1 paper, 2013). An increased concentration of glucose in the blood. "Taken together, above findings suggest the pathway of Irf-1-mediated hyperglycemia-dependent VSMC proliferation." (PMID 24119616, 2013). "Because overexpression of Irf-1 promotes the activation of Erk1/2 under high glucose conditions, the positive regulatory activity of Irf-1 could play a role in hyperglycemia-dependent VSMC proliferation." (PMID 24119616, 2013).
Hypertension (1 paper, 2017). The presence of chronic increased pressure in the systemic arterial system. "Hcmv-miR-UL112-3p targets IRF-1 and MICB, which are two key molecules in immunological, inflammatory and anti-infective responses, and IRF-1 and MICB repression by hcmv-miR-UL112-3p may be a unifying mechanism that evades the host response in the pathogenesis of hypertension." (PMID 28592251, 2017).
idiopathic inflammatory myopathies (1 paper, 2022). "Previous research reported that PSMB8, PSMB9 and PSMB10 expressed at significantly abundant levels in dendritic cells, monocytes, and CD8+ T-cells in idiopathic inflammatory myopathies, which correlated highest with STAT1, IRF1 and IFN-γ expression." (PMID 35933405, 2022).
injury (1 paper, 2013). Damage inflicted on the body as the direct or indirect result of an external force, with or without disruption of structural continuity. "Irf1 gene activation by reactive oxygen species is an early signal that promotes inflammation after ischemic renal injury." (PMID 24063402, 2013).
intrahepatic cholangiocarcinoma (1 paper, 2024). A carcinoma that arises from the intrahepatic bile duct epithelium in any site of the intrahepatic biliary tree. "Conversely, a modest increase in the expression of IFNA1, IFNB1, and IRF1 was observed in liver tissue sections from patients with intrahepatic cholangiocarcinoma." (PMID 38817870, 2024).